CDKN2A (cyclin dependent kinase inhibitor 2A)
Diseases named in the same sentence as CDKN2A in open-access papers (continued):
Sharing a sentence is not in itself a finding about the gene and the disease.
melanoma (continued). "Finally, a GWAS carried out in Spanish CDKN2A-negative patients identified a novel familial melanoma-associated locus at Chr11 harboring four genes (DLG2, PRSS23, FZD4, and TMEM135) with the strongest linkage evidence." (PMID 40869905, 2025). "In addition to sarcoma, germline CDKN2A is involved with melanoma, pancreatic, and breast cancers." (PMID 38730621, 2024). "In addition, in a subsequent IMI study focused on multiple melanomas, CDKN2A germline mutations were found in 4.4% of patients with a single primary melanoma (SPM) and in 19% of MPM cases, regardless of family history." (PMID 39596909, 2024). "However, when categorizing individuals based on melanoma case status, more significant positive correlations between CDKN2A pathogenic mutations and nevus counts were noted among family members not affected by melanoma." (PMID 38792946, 2024). "Instead, for skin not chronically exposed to the sun, the risk factor for melanoma can be endogenous, such as genetic susceptibility which is accountable for 8% to 10% of cases, with cyclin-dependent kinase inhibitor 2A (CDKN2A) as the main high-risk gene for melanoma." (PMID 38136297, 2023). "The YUMM1.1 parental melanoma cell line carries the genetic alterations of BRAFV600E mutation and deletion of phosphatase and tensin homolog (PTEN) and cyclin-dependent kinase inhibitor 2 (CDKN2A) and thus recapitulates the genetic profile of human metastatic melanoma." (PMID 37894438, 2023). "The purpose of this study was to perform a mutational analysis of the seven candidate melanoma susceptibility genes (ACD, BAP1, MC1R, MITF, POT1, TERF2IP, and TERT) in high-risk melanoma patients (familial melanoma and MPM) from southeastern Brazil, besides the CDKN2A and CDK4 genes." (PMID 37958811, 2023). "Moreover, cases with CDKN2A mutation had statistically significantly worse survival in comparison to melanoma cases with no CDKN2A mutations." (PMID 37626750, 2023). "However, there are also genome-wide copy number alterations in melanoma: amplification affects the melanoma oncogenes, as well as CCND1 (cyclin D1) and MITF, while loss of heterozygosity (LOH) or complete loss may affect CDKN2A (p16) and PTEN." (PMID 35628196, 2022). "In a panel of melanoma cell lines, the most prevalent alterations were found in CDKN2A, including copy number loss, methylation, or mutation in this gene, which resulted in a decreased or absent CDKN2A protein and increased palbociclib sensitivity." (PMID 35892870, 2022).
melanoma (continued). "Furthermore, there is no body-site concordance between CDKN2A-mutated familial melanomas, despite genetic has an impact on body-site distribution of naevi." (PMID 34442055, 2021). "Interestingly, we also found in both PDX and TCGA human tumors with mutations in melanoma (SKCM) a high expression of CDKN2A, which has not typically been classified as an oncogene." (PMID 34429404, 2021). "No significant DEGs were identified comparing melanoma patients with or without CDKN2A mutation." (PMID 34660619, 2021). "In human melanoma cell lines, loss of expression of the endogenous cyclin-dependent kinase inhibitor (CDKN2A), encoding for two distinct potent tumor suppressor proteins, p16INK4a and p14ARF, has shown to correlate with sensitivity to palbociclib; while Rb loss correlated with resistance." (PMID 34485433, 2021). "Like Pathway 1 to melanoma, dysplastic nevi are associated with activating mutations of BRAF or NRAS; additional mutation of the TERT promoter and, sometimes, hemizygous loss of CDKN2A are involved in the morphological progression to a “classical” (superficial spreading) melanoma in situ." (PMID 34277420, 2021). "A high nevus density does not, therefore, seem to be a melanoma risk factor for CDKN2A-mutation carriers, as confirmed by the observation of a high nevus count in CDKN2A carriers without melanoma diagnosis and few nevi in a number of CDKN2A-mutated melanoma patients." (PMID 34356093, 2021). "However, unlike A375 and RPMI cells, SK-MEL-3 cells have the functional form of the CDKN2A gene (cancer cell line mutation data), which may be crucial for KYNA biological activity toward melanoma cells." (PMID 34299117, 2021). "Thus, Lelliott and collaborators used a syngeneic BRAF V600E Cdkn2a-/-Pten-/- melanoma model and demonstrated that a triple therapy including BRAF, MEK, and CDK4/6 inhibitors led to an immediate tumor regression and improved mice survival, compared to the respective monotherapies." (PMID 34831311, 2021). "Furthermore, hereditary melanoma has been associated with germline mutations in high-risk melanoma susceptibility genes (CDKN2A, CDK4, TERT, POT1), polymorphisms in intermediate-risk melanoma susceptibility genes (BAP1, ACD, TERF2IP, MC1R and MITF), and germline missense substitutions in MITF." (PMID 32276436, 2020). "Interestingly, additional MPM and familial melanoma patients positive for CDKN2A or MITF (p.E318K) mutations did not harbour any of the suggestive variants identified in this study, supporting their probable relevant impact on MPM development." (PMID 32276436, 2020). "However, only one or no mutation was identified in the melanoma-susceptibility genes like CDKN2A and CDK4." (PMID 32083130, 2020). "However, although almost all pancreatic adenocarcinomas have inactivating alterations of this gene, until recently CDKN2A was not considered a PC susceptibility gene outside of the known association with melanoma and the melanoma-PC syndromes." (PMID 29216274, 2017). "Here we describe a 5’UTR c.-201_-198delinsCTTT CDKN2A variant (frequency 0.0028 based on 350 PC patients), which seems to be private to PC, since it has never been found in public databases nor in thousands of melanoma patients tested." (PMID 29216274, 2017).
melanoma (continued). "In doing so, the melanoma risk locus on chromosome 9 upstream of the MTAP/CDKN2A region reached genome-wide significance (without skin color as a covariate: per-allele odds ratio (OR) = 1.32, P = 3.0 x 10−7; with skin color as a covariate: per-allele OR = 1.42, P = 3.8 x 10−8)." (PMID 28973033, 2017). "Two previous studies have reported the significant relation between the A allele of CDKN2A rs3088440 polymorphism and the higher risk of melanoma, but other studies could not replicate such result." (PMID 28445979, 2017). "In human melanoma, p16 may be a more important tumor suppressor than Arf given that mutations (in exon 1β of CDKN2A) which exclusively affect Arf are generally not seen in melanoma tumors." (PMID 28915557, 2017). "Importantly, loss‐of‐function mutations in CDKN2A, and its binding partner, the product of the cyclin‐dependent kinase 4 (CDK4) gene, have been identified in highly melanoma‐prone families 8, 9, 10, firmly linking disruption of cell cycle control and melanoma risk." (PMID 26354726, 2016). "Also, CDKN2A D74 mutations are infrequent and have never been described in melanoma, either familial or sporadic, although a single report exists of a somatic CDKN2A D74E mutation (COSM13768) in a sporadic dysplastic nevus." (PMID 27519597, 2016). "As Denmark is a high incidence country for melanoma, there is a distinct possibility of phenocopies in families, and since only one person from each family was examined for CDKN2A and CDK4 mutations, it cannot be ruled out that mutations in some families have not been identified." (PMID 25803691, 2015). "However it is biologically plausible that variants affecting the genes MTAP, CDKN2A and ANRIL could have an important role in melanoma etiology." (PMID 23816148, 2013). "The goal of this study was to examine whether TL modified the risk of melanoma in melanoma-prone families with and without CDKN2A germline mutations." (PMID 23990928, 2013). "Consistent with a previous report that found that longer telomeres were associated with the development of sporadic CMM, we found that longer telomeres were also associated with increased CMM risk in melanoma families, although the association was only seen in cases without CDKN2A mutations." (PMID 23990928, 2013). "It was interesting that eleven of the molecules previously implicated in melanoma pathogenesis (described in the introduction) were identified as hubs in the Bayesian gene networks generated from our A375 cell dataset, including: BRAF, CCND1, RB1, PTEN, TYR, CDKN2A, and SOX10." (PMID 22536322, 2012). "However, subsequent studies revealed that CDKN2X was hypomethylated and overexpressed in melanized skin and melanomas, an unexpected characteristic based on the role of CDKN2A in human melanoma as currently understood, although CDKN2A is overexpressed in some other human cancers." (PMID 20230482, 2010). "However, only a small percentage of non-familial melanoma patients show inactivating mutations in the CDKN2A tumor suppressor gene." (PMID 19642975, 2009). "As ANRIL was localised within the 403 kb deletion in the French melanoma-NST family, it has been hypothesized that this new gene could be involved melanoma-NST syndrome families and in melanoma-prone families with no identified CDKN2A mutations." (PMID 18612309, 2008). "We monitored melanoma development in Tyr::NRASQ61K/°;Cdkn2a+/−;°/°;Cdh1F/F (Ecad) and Tyr::NRASQ61K/°;Cdkn2a+/−;Tyr::CreA/°;Cdh1F/F (∆Ecad) mice." (PMID 40500450, 2025).
melanoma (continued). "That both CDKN2A and the IFN gene cluster, frequently deleted in melanoma, are encompassed in FRA9A’s fragility zone introduces the possible involvement of C9orf72Exp." (PMID 39669124, 2024). "This higher CtBP1/BARS protein level commits cell proliferation and genome instability endorsing melanoma initiation and progression by CtBP1/BARS-mediated transcriptional repression of CDKN2A gene and Brca1 gene." (PMID 38711119, 2024). "The CDKN2A and PTEN tumor-suppressor genes were found to be inactivated in melanomas by either promoter methylation or focal deletion, the two events occurring in a mutually exclusive manner." (PMID 39518125, 2024). "Additional molecular oncogenic alterations (CDKN2A and TERT-p) are necessary for the development of DPN-like melanomas." (PMID 38247727, 2024). "The genes CDKN2A/B and CDK4 (also referred to as CDK genes), frequently altered in malignant melanoma, play a critical role in tumor development and progression." (PMID 38982214, 2024). "As in human mucosal melanomas, canine mucosal melanomas show a conserved deletion and insertion event on CFA 30 (HSA 15 in human melanoma), gain of c-MYC, and deletion of CDKN2A [LOE 4a-5, OEG A]." (PMID 38645640, 2024). "Focal hypermethylation of specific tumor suppressor gene promoters (e.g., PTEN, CDKN2A, and APC promoters) is commonly seen in melanomas, resulting in dysregulated intracellular signaling, cell cycle progression, apoptosis, and DNA repair." (PMID 39518125, 2024). "Herein, overexpression in the CDKN2A was correlated with apoptosis after the ATRA and SM combinational treatment in the melanoma cells, thus inducing tumor suppression and reduction in cell viability." (PMID 39758841, 2024). "The highest frequency of CDKN2A ALT was observed in patients with esophagogastric cancer, followed by thymic tumor, pancreatic cancer, gallbladder carcinoma and melanoma." (PMID 38822443, 2024). "Subsequently, these sets were modified to 9p21 (CDKN2A), 6p25 (RREB1), 11q13 (CCND1), and 8q24 (MYC), improving the discriminatory power in differentiating melanomas from nevi." (PMID 38247727, 2024). "Fluorescence in-situ hybridization (FISH) utilizing probes for genes RREB1 (6p25), cMYC (8q24), CDKN2A (p16)/CEN9, and CCND1 (11q13) has been shown to be sensitive and specific for differentiating Spitz nevi from spitzoid appearing melanoma." (PMID 37877026, 2023). "CDKN2A/B co-deletion was seen in 21 BMs (23.1% of cohort) across multiple cancer types including NSCLC (n = 9, 49.9%), melanoma (n = 6, 27.3%), breast (n = 2, 13.3%), gastrointestinal (n = 3, 25%), and renal cell carcinoma (n = 1, 25%)." (PMID 36915611, 2023). "In this study, we aimed to evaluate melanocytic tumors with spitzoid morphology using conventional melanoma FISH (RREB-1, CCND1, MYB and CEP6) and 9p21 FISH (CDKN2A) probes and compare the probe results with clinical and histopathological features." (PMID 38031947, 2023). "Although CDKN2A was first identified in 1994, followed by cyclin-dependent kinase 4 (CDK4) in 1996, most familial melanoma genes were only discovered after 2010 when next-generation sequencing technologies were introduced." (PMID 36901857, 2023). "In melanoma, DNA gene promoter hypermethylation with consequent transcriptional silencing has been observed for tumor suppressor genes as PTEN, CDKN2A and RASSF1A." (PMID 36768978, 2023).
melanoma (continued). "These include some canonical melanoma tumor-suppressive genes such as BRD9 and CDKN2A/CDKN2B, and several critical melanoma oncogenes like BIRC5 and YAP1." (PMID 37904237, 2023). "Meanwhile, CDKN2A, CXCR4 and RAD51 were significantly up-regulated in melanoma compared with normal skin except CDKN1A (significantly down-regulated)." (PMID 38070141, 2023). "In melanoma patients, CDKN1A (14%) and CDKN2A (34%) had a very high frequency of genetic aberration (inframe mutation, missense mutation, truncating mutation, amplification, deep deletion, mRNA high, mRNA low, protein high and low)." (PMID 38070141, 2023). "These ‘nevi and melanoma’ genes include BRAF, CDKN2A, MITF, some telomere length maintenance genes, and IRF4." (PMID 36834954, 2023). "Across cancers, patients in the CDKN2A del+ group had shorter survival, which was statistically significant in NSCLC, melanoma, renal cell cancer, and head and neck cancer (p-value < 0.05)." (PMID 35739333, 2022). "Genetic aberrations in CDKN2A are identified in about 40–60% of melanomas, and almost all lines derived from tumors have a genetically impaired CDKN2A/B-ARF pathway." (PMID 35565444, 2022). "The relative expression level of the hub genes was reverified in melanoma cell lines, and showed that HIF1A, IL1B, HMOX1, MMP3, CDKN2A and TIMP1 were upregulated, while PTEN, PRKCA, ATF3 and BRAF were downregulated in melanoma samples." (PMID 36226170, 2022). "For the level of mRNA expression in the TCGA database and melanoma cell lines, SLC39A14, PSMB4, CRELD2, CDKN2A and TIMP1 were higher in SKCM tissues than in normal skin tissues, and NDRG1, ATF3, and JUND had an opposite trend." (PMID 36226170, 2022). "RASSF1A is among the most frequently reported hypermethylated genes in melanoma, alongside RAR-β2, CDKN2A and MGMT." (PMID 34066022, 2021). "Functional CDKN2A and PTEN genes are characteristic features of SK-MEL-3 cells among all tested melanoma cell lines." (PMID 34299117, 2021). "Genotyping for MITF has been proposed in addition to CDKN2A/CDK4 testing for familial and multiple CM patients, and MITF-E318K carriers are encouraged to follow melanoma prevention programs and dermatologic surveillance." (PMID 34573422, 2021). "The CDKN2A/CDK4/6 pathway has a role in the G1–S transition in the cell cycle, which is dysregulated in BRAF and NRAS mutant melanomas." (PMID 34831002, 2021). "9p21 status was inferred based on transcriptional expression levels of both CDKN2A and MTAP, the same in the melanoma cohorts." (PMID 34556668, 2021). "We excluded the following genes that were methylated and deleted in melanoma: PTEN, BRIMS1, FERMT3 (KIND3), AKAP12 (SSeCKS), CDKN2A, APAF-1, MTAP and MEN1." (PMID 34639015, 2021). "Alterations in CDKN2A and in CCND1 are present in NRAS mutant melanomas in 70% and 10% of cases, respectively." (PMID 34831002, 2021). "Inborn errors in genes that control the G1 checkpoint, such as cyclin-dependent kinase inhibitor 2A (CDKN2A), enhance cellular proliferation and result in familial melanomas." (PMID 33800195, 2021). "CDKN2A/B deletions (9p21.3) were common between CYT-high and CYT-low melanomas (both primary and metastatic)." (PMID 33779796, 2021). "Genetic alterations in the INK4a/ARF (or CDKN2A) locus have been reported in many cancer types, including melanoma; head and neck squamous cell carcinomas; lung, breast, and pancreatic cancers." (PMID 33076392, 2020).